ALK (ALK receptor tyrosine kinase)
Diseases named in the same sentence as ALK in open-access papers (continued):
Sharing a sentence is not in itself a finding about the gene and the disease.
lung cancer (continued). "However, in other studies, induction of a Gas6-AXL pathway associated with EMT was shown to mediate EGFR TKI-induced resistance in lung cancer to cetuximab and erlotinib in HNSCC and to ALK inhibitors in ALKF1174L-positive human neuroblastoma cells." (PMID 29458371, 2018). "Similarly to the other lung cancer gene fusions, we firstly reported NRG1 rearrangement patterns in form of isolated 3′ signals, thus indicating a strength analogy with ALK and ROS1 fusions, where a 5′ gene deletion was frequently observed." (PMID 29515761, 2018). "Importantly, these models also displayed sensitivity to ALK inhibition and thus serve as valuable tools to explore the mechanisms of EML4-ALK induced lung cancer and response to ALK targeted therapies." (PMID 29455675, 2018). "The second study enrolled 343 patients who presented with ALK-positive lung cancer but had not previously received any systemic treatment for advanced disease." (PMID 29455675, 2018). "With the discovery of oncogenic driver mutations in epidermal growth factor receptor (EGFR) and rearrangements in anaplastic lymphoma kinase (ALK) and ROS1, there has been a paradigm shift from a “one size fits all” approach to lung cancer treatment to more precise and rational targeted therapy." (PMID 28396848, 2017). "Amongst others, microtubule-destabilizing agents are already approved as single or combination therapy in solid and hematologic cancers, but their discrete benefit in ALK fusion positive lung cancer has not been studied." (PMID 29189709, 2017). "In recent years, kinase targeted therapies have been developed that have shown improved efficacy in treatment of lung cancer compared to standard chemotherapy, e.g., epidermal growth factor receptor (EGFR) tyrosine kinase inhibitors and anaplastic lymphoma kinase (ALK) inhibitors." (PMID 29371917, 2017). "Most ALK-positive lung cancer patients are characterized by younger ages, no history of smoking or a history of light smoking, and adenocarcinoma histology." (PMID 28514730, 2017). "The 100% sensitivity of the ALK RT-PCR Kit for the identification of ALK-positive NSCLC cases, as shown here and by others independently, supports the use of the test as a screening approach for ALK in newly diagnosed lung cancer." (PMID 28763012, 2017). "Conversely, in one ALK-positive and two ALK-negative lung cancer patients with low anti-ALK levels by ELISA, Western blot showed no detectable bands." (PMID 29190913, 2017). "We analyzed ALK translocations from paired primary and metastatic lymph node tumors in 78 lung cancer patients who had not received TKI before the tissues were sampled." (PMID 29312572, 2017). "For instance, Hsp90 inhibitors have shown some promise in the treatment of ALK rearranged lung cancer, but have not been evaluated under the lens of second-line therapy." (PMID 28450729, 2017). "Early reports suggest a possible role of ALK in inducing an EMT phenotype in ALK-negative lung cancer cells." (PMID 27119231, 2016). "The effect of this mutation was dramatically less vs. all drugs when it was introduced instead to EML4-ALK, likely explaining why it has never been reported in resistant ALK+ lung cancer." (PMID 27009859, 2016). "Additional molecularly targetable biomarker discoveries include BRAF mutation testing for variable tumors like melanoma and craniopharyngioma and anaplastic lymphoma kinase (ALK) inhibitors and epidermal growth factor receptors in various subtypes of lung cancer." (PMID 27509178, 2016). "The unique expression pattern of SALL4 in lung cancer suggests that it can potentially be a good drug target for personalized medicine, targeting the lung cancer subtypes that cannot be treated by current targeted therapies like EGFR and ALK inhibitors." (PMID 27705911, 2016).
lung cancer (continued). "Therefore, our results suggests that EGFR-positive lung cancers exhibit more GGO components, less lymph node invasion, and a higher tendency to metastasize to other organs, compared to the KRAS- and ALK-positive subtypes." (PMID 27518729, 2016). "Intratumoral heterogeneity has been reported in lung cancer having both EGFR and ALK alterations." (PMID 26992209, 2016). "Sequential CTC counts in an index case of lung cancer with no evaluable tumor tissue treated with crizotinib showed six, three and eleven ALK-positive CTCs per 1.88 mL blood at baseline, partial response and post-progression time points, respectively." (PMID 26993609, 2016). "However, two clinically validated and FDA approved lung cancer predictive biomarkers (EGFR and ALK translocations) occur in only about 20% of lung adenocarcinomas and acquired resistance develops to first generation drugs." (PMID 28018791, 2016). "We assessed paired tumor and CTC samples from patients with ALK rearranged lung cancer (n = 14), ALK-negative lung cancer (n = 12), and healthy controls (n = 5) to derive discriminant CTC counts, and to compare ALK rearrangement patterns." (PMID 26993609, 2016). "Although EGFR and ALK inhibitors are established in EGFR mutant and ALK rearranged lung cancer, there are currently no molecularly targeted agents licensed for use in the remainder of adenocarcinomas (NSCLC-adeno-EGFRWT/ALKnon-rearranged)." (PMID 27441499, 2016). "ALK positive (defined as a rearrangement in the ALK gene) lung cancer patients are usually younger, non-smokers and adenocarcinoma histology." (PMID 26371045, 2015). "Anaplastic lymphoma kinase (ALK)-positive anaplastic large cell lymphoma (ALCL) is unusual among the lymphoma types, since it has a clear driver mechanism that it shares with other malignancies, especially ALK-positive lung cancer." (PMID 26640600, 2015). "The incidence or prevalence of simple or complex renal cysts in patients with either lung cancer or ALK-positive NSCLC has not previously been systematically evaluated." (PMID 25756473, 2015). "SOX2 was also not induced in other oncogene-dependentmodels, such as ALK-translocated lung cancer cells treated withcrizotinib, HER2-amplified breast cancer cells exposed to lapatinibor BRAF-mutant melanoma cells treated with AZD6244." (PMID 25686219, 2015). "Similarly, crizotinib (Xalkori), an anaplastic lymphoma kinase (ALK) inhibitor, has shown superiority compared with chemotherapy in lung cancer patients with ALK translocation." (PMID 26220301, 2015). "Crizotinib had been confirmed to be used in anaplastic lymphoma kinase (ALK) positive lung adenocarcinoma, but the efficacy in lung cancer with bone marrow metastasis was unknown." (PMID 25676401, 2015). "The clinical presentations are very similar to ALK positive lung cancers as ROS1 positive lung cancers tend to affect younger patients, never smokers and adenocarcinoma differentiation." (PMID 26371045, 2015). "In the past decade, lung cancer treatments have generally focused on targeted therapies such as epidermal growth factor receptor (EGFR) tyrosine kinase inhibitors and anaplastic lymphoma kinase (ALK) fusion protein inhibitors." (PMID 29546098, 2015). "In the current study, we have explored the mutational spectrum of 26 well-established cancer-related genes and ALK, RET, and ROS1 gene fusions by massive parallel sequencing in a large panel of thoroughly histopathologically classified primary LC and LCNEC lung cancers." (PMID 26124082, 2015). "In addition, we discuss potential future treatment strategies in ALK-TKI-naïve and -resistant patients with lung cancer harboring the EML4-ALK fusion gene." (PMID 25941796, 2015). "RET (rearranged during transfection) fusions are considered to be driver mutations in lung cancer because they are not found in association with changes in EGFR, KRAS, ALK or HER2." (PMID 24722523, 2014).
lung cancer (continued). "In addition, it has been reported that the lung cancer patient with IHC-positive and FISH-negative ALK had a dramatic response to crizotinib." (PMID 24422905, 2014). "ALK fusion proteins are HSP90 clients, and it has already been shown in preclinical and clinical studies that HSP90 inhibition is highly effective against EML4-ALK-positive lung cancer as well as against ALK-positive ALCL cells in vitro." (PMID 24509625, 2014). "Recognizing that the diffusion of diagnostic tests is a conditio sine qua non for the success of personalized lung cancer therapies, this study analyzed the diffusion of epidermal growth factor receptor (EGFR) and anaplastic lymphoma kinase (ALK) tests in Germany." (PMID 25562146, 2014). "Previous reports have shown that ALK+ lung cancers are characterized by younger patients, non-smokers or light smokers when compared with ALK- patients." (PMID 24422905, 2014). "Heat shock protein 90 is a chaperone protein that assists posttranslational folding of several proteins to stabilize and protect them from cellular stresses like heat or hypoxia, including critical proteins in lung cancer such as EGFR, HER2, MET, ALK, and others." (PMID 25505733, 2014). "In addition, fusions of ALK with other partners including TRK-fused gene TFG and KIF5B have also been described in lung cancer patients, but appear to be much less common than EML4-ALK." (PMID 25101240, 2014). "In addition to EML4-ALK, other ALK fusions have also been reported in lung cancer, including TFG-ALK, KIF5B-ALK and KLC1-ALK." (PMID 24992725, 2014). "The radiological characteristics of lung cancer with ALK rearrangement have hardly been studied, and there is a lack of data concerning the role of ALK rearrangement in nGGO lesions." (PMID 24885886, 2014). "Patients, similar to those with ALK-rearranged lung cancer, tend to be younger, never smokers, and have adenocarcinoma histology, although cases in squamous carcinoma have been reported." (PMID 25505733, 2014). "MED12 was identified as a common determinant of drug resistance using 24,000 shRNAs targeting 8000 human genes in a lung cancer line harboring a translocation between EML4 and the kinase ALK, which is sensitive to ALK inhibitors PF-02341066 (crizotinib) and NVP-TAE684." (PMID 24952721, 2014). "Based on the excellent results of the clinical trials with ALK-inhibitors, the importance of accurately identifying ALK positive lung cancer has never been greater." (PMID 25248157, 2014). "Lung cancer has entered an era of personalized therapy with treatment based on histologic subtypes (adenocarcinoma versus squamous) and the presence of molecular markers [epidermal growth factor receptor (EGFR) and anaplastic lymphoma kinase (ALK)]." (PMID 25295226, 2014). "However, since lung cancer is a common malignancy, an estimated 70,000 cases of ALK positive NSCLC occur world-wide each year, comprising the most common ALK-positive human malignancy." (PMID 24955213, 2014). "Until date, therapeutic decisions are heavily dependent on the histological subtype of lung cancer (SQC vs. non-SQC) and its molecular characteristics (e.g., EGFR mutation and ALK rearrangement states)." (PMID 24885169, 2014). "Because the prevalence of adenocarcinoma with ALK rearrangement is low compared to EGFR mutation, studies investigating various characteristics of ALK-positive lung cancer do not gather enough participants to yield consistent results." (PMID 24885886, 2014). "Common features of lung carcinoma harboring the ALK-fusion gene include the absence of lepidic growth and marked nuclear pleomorphism, a solid or acinar growth pattern, a substantial amount of extracellular mucus and the presence of mucus cells." (PMID 25295103, 2014). "Although FISH analysis is essential for the clinical usage of crizotinib in the United States, a previous study has demonstrated that initial screening by FISH alone does not detect all cases with ALK-positive lung carcinoma." (PMID 25295103, 2014).
lung cancer (continued). "The authors also reported on 6 NRAS mutant lung carcinoma cell lines and their sensitivity to the MEK inhibitors selumetinib and trametinib and their resistance to erlotinib (EGFR-TK inhibitor), crizotinib (ALK/MET/RON/ROS1 inhibitor) and linsitinib (IGF-1R inhibitor)." (PMID 25277205, 2014). "Because the incidence of ALK rearrangement is low in unselected NSCLC patients (2–5%), it is necessary to elucidate clinicopathological and molecular characteristics of ALK-positive lung cancer to improve screening efficiency." (PMID 23936355, 2013). "Previous studies have evaluated ALK rearrangement lung cancer, but the comprehensive analysis of ALK-rearranged lung cancers in Chinese has not well assessed." (PMID 23922677, 2013). "Concurrent activation of ALK and EGFR signaling pathways has been reported in the lung cancer cell lines, and these cell lines could only be suppressed by dual inhibition of both ALK and EGFR." (PMID 23951022, 2013). "Although most ALK-rearranged lung cancers are adenocarcinomas, other histological types should not exclude its presence." (PMID 23922677, 2013). "Herein, we identified 44 cases of ALK-rearranged samples by fluorescent in-situ hybridization (FISH), immunohistochemistry (IHC), and reverse transcription polymerase chain reaction (RT-PCR) in a large number of surgically resected lung cancers." (PMID 23922677, 2013). "Recent studies have demonstrated that lung cancers harboring ALK rearrangements do not respond to EGFR-specific tyrosine kinase inhibitors, but benefit from a small molecule inhibitor targeting the ALK kinase (ie, crizotinib [Xalkori®, Pfizer, Inc.])." (PMID 23198868, 2012). "Patients with ALK positive lung cancers tend to be younger, with little or no exposure to tobacco and have mostly adenocarcinomas." (PMID 23675251, 2012). "In lung cancer, 3 fusion partners of ALK have been reported—EML4, TFG, and KIF5B—although the presence of TFG-ALK in lung cancer has not yet been proven with histopathological evidence." (PMID 22347464, 2012). "In lung cancer, the primary ALK fusion detected was identified as EML4-ALK, followed by TFG-ALK and KIF5-ALK, although other unknown fusions may also exist which can not be detected due to limits of present technology." (PMID 20624322, 2010). "Lung cancer epitomises precision oncology, which centers on targeting molecular alterations such as Epidermal Growth Factor Receptor (EGFR), Kirsten Rat Sarcoma Viral oncogene homolog (KRAS) G12C and Anaplastic Lymphoma Kinase (ALK), found in 40%–50% of lung adenocarcinomas." (PMID 41333367, 2025). "Interestingly, among the 13 ribonucleases, only RNase1 (R1), but not the others, bound to endogenous ALK in H1299 human lung cancer cells expressing WT ALK." (PMID 40246819, 2025). "The LUAD dataset lacked mutational profiling such as EGFR, ALK, or KRAS status, which are key determinants of prognosis in lung cancer and could influence spatial associations with survival." (PMID 40723219, 2025). "In lung cancer, BRAF V600E typically occurs in never-smokers, with adenocarcinoma histology, and lacks other common driver mutations, resembling other oncogene-driven cancers such as EGFR or anaplastic lymphoma kinase (ALK)-mutated tumors." (PMID 40332392, 2025). "There were no identified cases of ALK or ROS1 translocation amongst lung cancer cases." (PMID 41294703, 2025). "In both EPHA4 wild-type or EPHA4 knockout lung cancer cells, RNase1 could bind to ALK and ALK did not bind to EPHA4, which suggested that the RNase1-ALK interaction was independent of EPHA4 in lung cancer cells." (PMID 40246819, 2025). "Here, we integrate studies in patient-derived and immunocompetent lung cancer models and clinical specimens obtained from patients on targeted therapy to uncover a focal adhesion kinase (FAK)-YAP signaling axis that promotes residual disease during oncogenic EGFR-, ALK-, and KRAS-targeted therapies." (PMID 38702301, 2024).
lung cancer (continued). "Among all types of lung cancer, non-small cell lung cancer (NSCLC) accounts for approximately 80–85%, and 5-year survival rates for NSCLC are estimated to be 6.1% for those diagnosed between 2009 and 2015, and anaplastic lymphoma kinase (ALK) rearrangements occur in approximately 5–8% of patients." (PMID 38331773, 2024). "As it is unlikely that patients with other subtypes were prescribed ALK TKIs, as their use is not indicated in other subtypes, our data may still have included other subtypes of lung cancer." (PMID 39851929, 2024). "In a real-world study of patients with lung cancer in a community-based Ontario hospital, a median turnaround time of 36.5 days (interquartile range: 29.5–47 days) was reported for tissue testing results (EGFR and ALK), with only 20% of patients having biomarker results at the first consultation." (PMID 39451753, 2024). "The evidence of ABCP in patients with ALK-positive lung cancer is limited, but not negligible." (PMID 38610927, 2024). "Unique genomic characteristics of human never-smoker lung cancer include somatic activating point mutations or fusions affecting EGFR (45%), anaplastic lymphoma kinase (ALK; 5–11%), ROS (1.5–6%), human epidermal growth factor receptor 2 (HER2; 3–5%) and rearranged during transfection (RET; 2%)." (PMID 39902337, 2024). "Nonetheless, to the best of our knowledge, these CT signs may be found in most patients with advanced lung cancer and have no predictive value in correlating with ALK-rearranged lung cancer in the pre-advanced stages." (PMID 36823653, 2023). "Variant-specific PCR was performed for 744 tumors with a normal 5′/3′-end expression ratio: there were no rearrangements in 172 EGFR/ALK/ROS1/RET/MET-negative lung cancers and 125 pediatric tumors, while NTRK3 fusions were detected in 2/447 (0.5%) non-lung adult malignancies." (PMID 37762506, 2023). "All patients with primary lung cancer had adenocarcinoma histology, 14 (56%) had a mutation in the epidermal growth factor receptor (EGFR) gene, four (16%) had rearrangements of the anaplastic lymphoma kinase (ALK) gene, and six (28%) did not have any common somatic mutation detected." (PMID 35770957, 2023). "Furthermore, a prospective cohort study involving 341 patients with lung cancer, including 26 positive for ALK fusion gene, indicated a higher cumulative VTE incidence rate of 26.9% in ALK fusion gene-positive patients (9.2% in ALK fusion gene-negative patients)." (PMID 36357710, 2023). "A retrospective study of patients with ALK fusion gene-positive lung cancer demonstrated a significantly higher VTE incidence among 422 patients with ALK fusion gene-positive lung cancer than that in patients who were negative for the fusion gene (42.7% vs. 28.6%, p < 0.0001)." (PMID 36357710, 2023). "This cohort study enrolled 1374 lung cancer patients with no detected EGFR and ALK mutations." (PMID 36969059, 2023). "The prolongation of mPFS in the non-EGFR/ALK group could be related to the fact that EGFR-mutant lung cancer patients had prior targeted therapy and therefore, worse performance status and more tumor burden at start of chemoIO therapy." (PMID 35884533, 2022). "Given that ALK NSCLC is often but does not exclusively affect a light-/never-smoking population, the focus has been on other risk factors including modifiable environmental factors that have evidence to increase lung cancers more broadly." (PMID 36003760, 2022). "PD-L1-enhancing oncogenes, such as EGFR, ALK, MET, AKT, MYC, and CDK5, were not identified as hits in this study because KRAS mutations in lung cancer cell lines (H2009 and H460) could establish distinct PD-L1 regulatory axes." (PMID 36357569, 2022). "The baseline characteristics of the study patient population were consistent with those reported in lung cancer patients with ALK-rearranged tumors, who are often younger than the general lung cancer population and present light or non-smoking habits and adenocarcinoma histology." (PMID 35720977, 2022).